SERBP1 (SERPINE1 mRNA binding protein 1)
Description:
Ribosome-binding protein that promotes ribosome hibernation, a process during which ribosomes are stabilized in an inactive state and preserved from proteasomal degradation. Acts via its association with EEF2/eEF2 factor, sequestering EEF2/eEF2 at the A-site of the ribosome and promoting ribosome stabilization and storage in an inactive state (By similarity). May also play a role in the regulation of mRNA stability: binds to the 3'-most 134 nt of the SERPINE1/PAI1 mRNA, a region which confers cyclic nucleotide regulation of message decay. Seems to play a role in PML-nuclear bodies formation.
Synonyms: PAI-RBP1; PAIRBP1; CGI-55; CHD3IP; HABP4L; Hero45; DKFZP564M2423
Tractability: Small molecule: a structure with a bound ligand is known. PROTAC: UniProt records ubiquitination sites on it; ubiquitination databases record sites on it; its protein half-life has been measured.
Gene: Protein-coding gene on chromosome 1 (67,407,810 to 67,430,415, reverse strand). Ensembl gene ENSG00000142864.
Subcellular location: Cytoplasm; Nucleus; Cytoplasm, perinuclear region
Subcellular location (Human Protein Atlas): Cytosol
Gene Ontology:
Molecular function: cadherin binding; mRNA 3'-UTR binding; protein binding; ribosome binding; RNA binding; SUMO binding; translation repressor activity; translation elongation factor binding
Biological process: negative regulation of translation; PML body organization; ribosome hibernation; regulation of mRNA stability
Cellular component: cytoplasm; cytosol; extracellular exosome; membrane; nucleus; perinuclear region of cytoplasm
Genetic constraint (gnomAD): Loss-of-function variants: 6 observed, 46.26 expected, observed/expected ratio (o/e) 0.13, 90% interval 0.07 to 0.26. The upper end of that interval is the gene's LOEUF score, 0.26, which puts it in group 1 of 6, group 1 being the genes least tolerant of losing a copy. Missense variants: 339 observed, 520.6 expected, observed/expected ratio (o/e) 0.65, 90% interval 0.6 to 0.71. Synonymous variants: 166 observed, 176.92 expected, observed/expected ratio (o/e) 0.94, 90% interval 0.83 to 1.07.
Homologues: Orthologues: chimpanzee SERBP1 (100% identical), macaque SERBP1 (99% identical), rabbit SERBP1 (99% identical), dog SERBP1 (99% identical), pig SERBP1 (99% identical), mouse Serbp1 (98% identical), rat Serbp1 (95% identical), guinea pig SERBP1 (94% identical), tropical clawed frog serbp1 (81% identical), zebrafish serbp1a (74% identical), zebrafish serbp1b (72% identical), Drosophila melanogaster vig (35% identical), and 2 more. Paralogues in human: HABP4 (45% identical).
Diseases named in the same sentence as SERBP1 in open-access papers:
SERBP1 is named in the same sentence as 71 diseases in open-access papers, as found by Europe PMC text mining. Sharing a sentence is not in itself a finding about the gene and the disease. The quoted sentences say what the papers report.
glioblastoma (13 papers, 2013 to 2026). The most malignant astrocytic tumor (WHO grade IV). "High SERBP1 expression in glioblastoma multiform (GBM) is linked to poor patient outcome and response to therapy while in vitro and in vivo studies showed that expression levels of SERBP1 affect several related cancer phenotypes, stemness, neuronal differentiation and tumor growth." (PMID 34631798, 2021). "We further demonstrate that SERBP1 regulates mTOR expression in glioblastoma cell lines through G4 elements in the mTOR 5' UTR, and that SERBP1 depletion synergizes with mTOR inhibition to reduce cell growth." (PMID 41846982, 2026). "SERBP1 expression in the brain is lower than in other organs and is increased in glioblastoma and Alzheimer’s brains, as shown in this study." (PMID 39937575, 2025). "In glioblastoma, SERBP1 functions as a central regulator of metabolic pathways, coordinating the expression of related enzymes and associated factors implicated in serine biosynthesis, one-carbon, and 5'-methylthioadenosine (MTA) cycles." (PMID 39937575, 2025). "Increased level of SERBP1 has been observed in various cancers, including acute lymphoblastic leukemia, breast cancer, ovarian carcinoma, glioblastoma and squamous lung-cell carcinoma." (PMID 38470932, 2024). "SERBP1 is a member of the RG/RGG family of RBPs, which is markedly overexpressed in glioblastoma and in prostate, ovarian, and liver cancer and is associated with poor outcomes." (PMID 35892886, 2022). "SERBP1 regulates One-carbon metabolism and epigenetic modification of histones, and increased SERBP1 expression in cancers such as leukemia, ovarian, prostate, liver and glioblastoma is correlated with poor patient outcomes." (PMID 34631798, 2021). "The over-expression of SERBP1 was reported in glioblastoma, ovarian, breast, prostate, lung and colon cancer." (PMID 33245729, 2020). "We identify the RNA-binding protein SERBP1 as a novel regulator of glioblastoma (GBM) development." (PMID 32762776, 2020). "In glioblastoma (GBM), SERBP1 promotes malignant progression by regulating tumor metabolic reprogramming." (PMID 41227349, 2025). "Although many functional features tend to overlap between HABP4 and SERBP1, in relation to cancer the data so far point in opposite directions, since SERBP1 has been reported to be over-expressed in several cancer settings, including ovary, breast, colon, prostate, glioblastoma and lung cancer." (PMID 33245729, 2020). "For example, SERBP1 (Serpine1 mRNA-binding protein 1) is a member of the RG/RGG family of RNA-binding proteins and has been recognized as a novel oncogenic factor in glioblastoma, and the high SERBP1 expression correlates with poor patient survival and adverse response to chemo- and radiotherapy." (PMID 32873282, 2020).
breast carcinoma (11 papers, 2008 to 2026). "Surprisingly, nuclear SERBP1 expression in breast carcinoma was significantly associated with favourable prognosis in recurrence-free survival analysis which is inverse to the prognostic impact of the proteins uPA/PAI-1." (PMID 23236990, 2012). "SERBP1 is a molecule which is thought to regulate the activity of the important breast cancer recurrence associated protein PAI-1." (PMID 23236990, 2012). "Surprisingly, in the survival analyses abundant SERBP1 expression was associated with favourable prognosis which is inverse to the prognostic impact of the PAI-1 protein level because high PAI-1 protein levels are known to indicate unfavourable prognosis in human breast cancer." (PMID 23236990, 2012). "We transfected breast cancer cells with Flag‐SERBP1 plasmids and conducted an exogenous RIP experiment." (PMID 40145796, 2025). "Previous report showed that the overexpression of SERBP1 in human breast cancer is correlated with favorable prognosis." (PMID 32201535, 2020). "In further studies we are going to analyse the exact function of SERBP1 in the development of breast cancer and its interaction with the progesterone receptor and PAI-1 in this context." (PMID 23236990, 2012). "Two independent cohorts of breast cancer specimens arranged on two different tissue microarrays were analysed for SERBP1 expression by immunohistochemistry." (PMID 23236990, 2012). "This is the first study to present a systematic characterisation of SERBP1 expression in human breast cancer and normal breast tissue at both the mRNA and the protein level." (PMID 23236990, 2012). "In four breast cancer samples the rate of SERBP1 mRNA was slightly lower than in the corresponding normal tissues." (PMID 23236990, 2012). "However, the role of membrane progesterone receptors (PGRMC1 and SERBP1), which are uniformly expressed across breast cancer cells, remains to be elucidated in these cells." (PMID 30337371, 2018). "The RNA-binding protein SERBP1 is abundantly expressed in human breast cancer and may represent a novel breast tumour marker with prognostic significance." (PMID 23236990, 2012). "Interestingly, overall survival analysis also displayed a tendency (P = 0.09) towards favourable prognosis when SERBP1 was overexpressed in breast cancer." (PMID 23236990, 2012). "Therefore we next determined SERBP1 protein expression in extracts of cryoconserved human breast cancer tissues with low (n = 8) and high (n = 8) levels of the protein PAI-1 as determined by the FEMTELLE® ELISA test." (PMID 23236990, 2012). "SERBP1 protein expression was analysed in two independent cohorts on tissue microarrays (TMAs), an initial evaluation set, consisting of 193 breast carcinomas and 48 normal breast tissues, and a second large validation set, consisting of 605 breast carcinomas." (PMID 23236990, 2012). "In summary, SERBP1 is a potential prognostic marker in human breast carcinoma." (PMID 23236990, 2012). "However SERBP1 expression was slightly higher in three breast carcinomas compared with the matched normal breast specimens." (PMID 23236990, 2012). "However, recurrence-free survival analysis showed a significant correlation (P = 0.008) between abundant SERBP1 expression in breast carcinoma and favourable prognosis." (PMID 23236990, 2012). "We analysed the results especially in correlation to clinicopathological data like hormone receptor status, HER2 status and patient survival in order to validate SERBP1 as a new prognostic marker and potential drug target in the treatment of human breast cancer." (PMID 23236990, 2012). "We next analysed SERBP1 mRNA expression in matched pairs of normal and malignant cryoconserved human breast tissue to decipher whether SERBP1 gets deregulated during breast cancer development as it has been shown in ovarian cancer." (PMID 23236990, 2012).
breast carcinoma (continued). "In addition, a collection of benign (n = 2) and malignant (n = 6) mammary cell lines as well as breast carcinoma lysates (n = 16) were investigated for SERBP1 expression by Western blot analysis." (PMID 23236990, 2012). "In addition, SERBP1 expression was heterogeneous in normal and breast cancer specimens." (PMID 23236990, 2012). "Interestingly, in our initial cohort of breast carcinomas (n = 193) we found a trend between abundant SERBP1 expression and favourable prognosis in recurrence-free survival (RFS; P = 0.301) pointing towards a potential protective role of SERBP1 in breast cancer development." (PMID 23236990, 2012). "In breast cancer, KAT2A‐mediated RCC2 lactylation at K124 facilitates RCC2 recruitment of SERBP1, stabilizing MAD2L1 mRNA and promoting progression." (PMID 41454479, 2026). "Five of these antigens (VPS35, ARPC2, SERBP1, KRT8, and PDIA6) were selected because they inhibited human breast cancer survival across two aggressive breast cancer subtype cell lines (HER2 positive and triple negative)." (PMID 33976232, 2021). "Four of the antigens (VPS35, SERBP1, KRT8, and PDIA6) decreased growth of the tumors in both mouse mammary tumor models." (PMID 33976232, 2021). "Elevated expression levels of RCC2, SERBP1, and MAD2L1 were positively correlated with poor prognosis and shorter survival times in breast cancer patients, suggesting that they may serve as biomarkers for clinical prognosis assessment." (PMID 40145796, 2025). "In summary, our survival analyses showed a correlation between nuclear SERBP1 expression and favourable prognosis which is inverse to the prognostic impact of PAI-1 as high PAI-1 protein levels are related to unfavourable prognosis in human breast cancer [10." (PMID 23236990, 2012). "SERBP1 is not differentially expressed in breast carcinoma compared to normal breast tissue, both at the RNA and protein level." (PMID 23236990, 2012). "In human breast cancer expression of SERBP1 has not been examined so far." (PMID 23236990, 2012). "This explanation is encouraged by our Western blot analysis where breast carcinoma extracts with high PAI-1 protein levels showed weak SERBP1 protein expression by trend and vice versa breast carcinoma extracts with low PAI-1 protein levels showed abundant SERBP1 protein expression." (PMID 23236990, 2012).
ovarian carcinoma (6 papers, 2012 to 2025). A malignant neoplasm originating from the surface ovarian epithelium. "More importantly, overexpression of SERBP1 was detected in ovarian cancer and is significantly associated with advanced tumor stages." (PMID 33526047, 2021). "Until now, SERBP1 overexpression was just shown in human ovarian carcinomas and was associated with advanced tumour stage." (PMID 23236990, 2012). "Receiver Operating Characteristic (ROC) curve analysis shows that the area under the curve (AUC) of SERBP1 for diagnosing ovarian cancer is 0.86 (95% CI: 0.80–0.92), with a sensitivity of 81.7% and a specificity of 78.1%." (PMID 41227349, 2025). "In ovarian cancer, immunohistochemical analysis shows that the positive expression rate of SERBP1 in tumor tissues is 78.3% (n = 120), which is significantly higher than that in normal ovarian tissues (12.5%, n = 32)." (PMID 41227349, 2025). "Mechanistically, SERBP1 was identified as a direct target and functional effector of miR-362-3p in ovarian cancer." (PMID 33526047, 2021). "Taken together, our study determined that the function of the miR-362-3p-SERBP1 axis was largely a mechanism to inhibit ovarian cancer occurrence and development." (PMID 33526047, 2021). "Due to the pivotal role of SERBP1 in ovarian cancer, we finally decided to verify it as a target gene of miR-362-3p." (PMID 33526047, 2021). "miR-362-3p inhibited the development and progression of ovarian cancer by directly binding to the target gene SERBP1." (PMID 33526047, 2021). "miR-362-3p inhibits the development and progression of ovarian cancer by directly binding its target gene SERBP1." (PMID 33526047, 2021). "Recently, overexpression of the PAI1 mRNA binding protein (SERBP1) was also detected in ovarian cancer where it significantly correlated with advanced tumour stage." (PMID 23236990, 2012). "Moreover, the findings of this study revealed that miR-362-3p regulates the expression of SERBP1 in ovarian cancer growth and metastasis." (PMID 33526047, 2021). "Moreover, CCK-8 and cell cycle analysis assays showed that the miR-362-3p mimic inhibited ovarian cancer cell proliferation, whereas SERBP1 overexpression significantly reversed this inhibitory effect." (PMID 33526047, 2021). "To determine whether SERBP1 is an effector of miR-362-3p in ovarian cancer, we cotransfected the miR-362-3p mimic and pcDNA3.1(+)-SERBP1 (SERBP1 overexpression) vector into CAOV3 cells to conduct rescue experiments." (PMID 33526047, 2021). "Recently, overexpression of SERBP1 was described in human ovarian cancer for the first time." (PMID 23236990, 2012). "SERBP1, a protein that is supposed to regulate the stability of PAI-1 mRNA, may play a role in gynaecological cancers as well, since upregulation of SERBP1 was described in ovarian cancer recently." (PMID 23236990, 2012). "SERBP1 is overexpressed in ovarian cancer epidermal cells and is significantly correlated with the progression and grade (FIGO) of ovarian cancer, suggesting its important biological functions in cancer invasion and metastasis." (PMID 36213507, 2022). "Moreover, we identified that miR-362-3p repressed ovarian cancer proliferation by directly combining with and regulating SERPINE1 mRNA-binding protein 1 (SERBP1)." (PMID 33526047, 2021). "Next, we detected SERBP1 protein and mRNA expression in normal ovarian cell lines (IOSE80) and ovarian cancer cell lines (OVCAR3, CAOV3, HO-8910, and SKOV3) and noticed that the protein and mRNA expression of SERBP1 was significantly lower in IOSE80 cells than in all ovarian cancer cells tested." (PMID 33526047, 2021).
glioma (3 papers, 2016 to 2025). A benign or malignant brain and spinal cord tumor that arises from glial cells (astrocytes, oligodendrocytes, ependymal cells). "High SERBP1 expression was associated with poor survival in glioma patients in the TCGA and CGGA cohorts." (PMID 32762776, 2020). "We further examined whether SERBP1 expression was associated with glioma grades." (PMID 32762776, 2020). "SERBP1 is highly expressed in neuronal and glioma stem cells and a decrease in its levels is required for neuronal differentiation." (PMID 39937575, 2025). "SERBP1 is highly expressed in neuronal and glioma stem cells and its levels drop significantly during neurogenesis." (PMID 39937575, 2025). "SERBP1 expression was closely correlated with WHO grade of glioma (low grade vs. high grade, chi-square test, P = 0.002)." (PMID 32762776, 2020). "We evaluated the role of SERBP1 as an oncogenic factor in glioma/GBM and its potential impact on patient survival and response to therapy." (PMID 32762776, 2020). "Despite variable expression of SERBP1 in gliomas, GBM samples had noticeably higher expression of SERBP1 compared to LGG samples." (PMID 32762776, 2020). "SERBP1 knockdown causes delay in tumor growth and impacts cancer-relevant phenotypes in GBM and glioma stem cell lines." (PMID 32762776, 2020). "By bridging these two processes, SERBP1 enhances glioma stem cell phenotypes and contributes to GBM poorly differentiated state." (PMID 32762776, 2020). "Overall, our results indicate that SERBP1 contributes to GBM poorly differentiated state and glioma stem cell phenotypes by repressing genes implicated in neuronal differentiation and neuronal function." (PMID 32762776, 2020). "Finally, we evaluated the impact of SERBP1 on glioma stem cell (GSC) survival and proliferation." (PMID 32762776, 2020). "SERBP1 was positive in 28.6% of those with grade I gliomas, 55.6% of those with grade II gliomas, 83.3% of those with grade III gliomas, and 89.0% of those with grade IV gliomas (P < 0.001)." (PMID 32762776, 2020). "Moreover, 71.2% of patients with grade IV (GBM) had high positive staining for SERBP1, significantly more than grade I (7.1%), grade II (40.7%), and grade III (61.1%) gliomas (P < 0.001)." (PMID 32762776, 2020). "Finally, using the glioma cohort from the Shanghai Changzheng, we determined that AKT1 and SERBP1 display good expression correlation based on immunostaining." (PMID 32762776, 2020). "Notably, SERBP1 shows higher expression in GBM (TCGA samples) compared to normal brain and LGG (low-grade glioma, grade II)." (PMID 32762776, 2020).
hepatoma (3 papers, 2012 to 2022). "An explanation for this inverse relationship might be the degradation of PAI-1 mRNA by binding of the SERBP1 protein to it as it was described in rat hepatoma cells previously and which was underlined by our Western blot analyses by trend." (PMID 23236990, 2012). "The SERBP1 protein greatly increases the degradation of PAI-1 mRNA in rat hepatoma cells." (PMID 23947536, 2013). "Indeed, in rat hepatoma cells it could be shown that binding of SERBP1 protein to the PAI1 mRNA leads to degradation and destabilisation of PAI1 mRNA." (PMID 23236990, 2012). "An explanatory model for this inverse relationship between SERBP1 and PAI-1 could be the finding in rat hepatoma cells where high SERBP1 protein levels lead to degradation of PAI-1 mRNA and consecutively to low PAI-1 protein levels." (PMID 23236990, 2012).